ANTXR2 (ANTXR cell adhesion molecule 2)
Diseases named in the same sentence as ANTXR2 in open-access papers:
ANTXR2 is named in the same sentence as 55 diseases in open-access papers, as found by Europe PMC text mining. Sharing a sentence is not in itself a finding about the gene and the disease. The quoted sentences say what the papers report.
hyaline fibromatosis syndrome (20 papers, 2014 to 2026). "Whole exome sequencing identified a homozygous pathogenic frameshift mutation in the ANTXR2 gene (c.1074del; p.Ala359fs), confirming the diagnosis of infantile systemic hyalinosis." (PMID 41841067, 2026). "WES analysis highlighted the de novo monoallelic variant c.1069del that introduced a premature stop codon (p.Ala357Profs*52) in the ANTXR2 gene; this variant was reported in ClinVar in patients with hyaline fibromatosis syndrome." (PMID 40259928, 2025). "In fact, biallelic ANTXR2 variants have been known to cause hyaline fibromatosis syndrome (OMIM #228600)." (PMID 40259928, 2025). "Specifically, pathogenic variants in ANTXR2 have been associated with hyaline fibromatosis syndrome, while ANTXR1 pathogenic variants are responsible for GAPO syndrome." (PMID 38653789, 2024). "Hyaline fibromatosis syndrome is a rare progressive autosomal recessive connective tissue disorder caused by a mutation in the ANTXR2/CMG2 gene." (PMID 37264371, 2023). "Hyaline fibromatosis syndrome (HFS) is a rare autosomal recessive disorder caused by mutations in the gene for anthrax toxin receptor-2 (ANTXR2)." (PMID 34627224, 2021). "Hyaline fibromatosis syndrome (HFS) is a rare clinical condition in which bi-allelic variants in ANTXR2 are associated with extracellular hyaline deposits." (PMID 31455396, 2019). "Additionally, mutations in the ANTXR2 gene have been linked to various autoimmune diseases, including Hyaline Fibromatosis Syndrome (HFS), Ankylosing Spondylitis (AS), Juvenile Hyaline Fibromatosis (JHF), and Infantile Systemic Hyalinosis (ISH)." (PMID 38674361, 2024). "ANTXR2 mutations in a family were linked to the occurrence of Juvenile Hyaline Fibromatosis (JHF)." (PMID 38674361, 2024). "The study implicates certain SNPs in Hyaline Fibromatosis Syndrome and suggests others as potential candidates for hypertension related to the ANTXR2 gene." (PMID 38674361, 2024). "Hyaline fibromatosis syndrome (HFS), resulting from ANTXR2 mutations, is an ultra-rare disease that causes intestinal lymphangiectasia and protein-losing enteropathy (PLE)." (PMID 33147779, 2020). "ANTXR2 or ANTXR cell adhesion molecule 2 (also known as HFS; ISH; JHF; CMG2; CMG-2) is well-known to be involved in the development of Hyaline fibromatosis syndrome (HFS) through certain mutations." (PMID 31996736, 2020).
anthrax (18 papers, 2011 to 2024). "Anthrax toxin causes anthrax pathogenesis and expression levels of ANTXR2 (anthrax toxin receptor 2) are strongly correlated with anthrax toxin susceptibility." (PMID 26703731, 2015). "The nature of human interactions with anthrax disease might make the ANTXR2 locus particularly susceptible to soft selective sweeps over time." (PMID 34782625, 2021). "So we focused our study on the CREB-binding sites containing SNPs, and tested whether these SNPs would affect ANTXR2 expression and cell susceptibility to anthrax toxins." (PMID 26703731, 2015). "To understand how a zoonotic disease may have influenced human evolution, we study changes in human expression of anthrax toxin receptor 2 (ANTXR2), which encodes a cell surface protein necessary for Bacillus anthracis virulence toxins to cause anthrax disease." (PMID 34782625, 2021). "Moreover, ANTXR2 expression was slightly higher in blood cells isolated from hunter gatherers than in nearby agricultural populations within Africa31, potentially consistent with agricultural populations being at higher risk of exposure to anthrax disease." (PMID 34782625, 2021). "In this study, because of their significant role in the pathogenesis of anthrax, the ANTXR2 gene has been assessed for SNPs and examined for their impact on interaction with PA." (PMID 38674361, 2024). "In addition to changes compared with other primates, ANTXR2 expression varied by one order of magnitude within humans, suggesting that a number of genetic variants may still exist within human populations associated with anthrax susceptibility." (PMID 34782625, 2021). "We also observe multiple genetic signatures consistent with recent positive selection driving a European-specific decrease in ANTXR2 expression in multiple tissues affected by anthrax toxins." (PMID 34782625, 2021). "As the major receptor for anthrax toxin in vivo, anthrax toxin receptor 2 (ANTXR2) plays an essential role in anthrax toxin action by providing the toxin with a high-affinity binding anchor on the cell membrane and a path of entry into the host cell." (PMID 26805886, 2016). "Most recent studies have suggested that the disulfide bond in the immunoglobulin (Ig)-like domain of ANTXR2 plays an essential role in anthrax toxin action." (PMID 26805886, 2016). "Here, we provide an updated review of the most recent research progress concerning ANTXR2, the major receptor for anthrax toxin in vivo, in anthrax toxin action." (PMID 26805886, 2016). "Given the association of deleterious SNPs with diverse diseases, utilizing tolerated SNPs identified in the study—shown to reduce the binding affinity between the protective antigen and ANTXR2 gene—may prove effective as a biomarker against anthrax." (PMID 38674361, 2024). "In addition to playing a significant role in the pathogenesis of anthrax, ANTXR2 has been shown to play a role in other conditions as well." (PMID 38674361, 2024). "Most studies of ANTXR2 have focused on its role in the pathogenesis of anthrax." (PMID 36915057, 2023). "Consistent with the hypothesis that anthrax disease in Europeans led to a relatively recent population-specific adaptive response, we found a candidate selective sweep upstream of ANTXR2." (PMID 34782625, 2021). "Additionally, tolerated SNPs identified could serve as biomarkers for anthrax due to their impact on the binding affinity between the protective antigen and the ANTXR2 gene." (PMID 38674361, 2024). "Because ANTXR2 recruits CREB for transcription, SNPs in these TFBS might not only affect gene transcription in physiological conditions but also alter host susceptibility to anthrax infection." (PMID 26703731, 2015). "Whilst the discovery of a third PA receptor on the host cell may prove to have interesting implications for efforts to develop monoclonal antibodies, blocking PA binding to host cell receptors, currently ANTXR2/CMG2 remains the most physiologically relevant receptor during anthrax infection." (PMID 23162703, 2012).
anthrax (continued). "Thus, our analysis identified population-level differences in ANTXR2 expression affecting the majority of tissues, with a lower expression in Europeans as would be expected based on the likely direction of positive selection due to interactions with anthrax disease." (PMID 34782625, 2021). "Thus a tenfold increase in human ANTXR2 expression, similar to changes found in non-human primates, increased the effect of anthrax toxins on cellular phenotypes and confirmed that ANTXR2 expression causes changes in anthrax toxin sensitivity in human hematopoietic cells." (PMID 34782625, 2021). "By generating ANTXR2-/- and ANTXR1-/- null mice, an important finding was made to reveal the differential roles of the two receptors in anthrax infection in vivo." (PMID 26805886, 2016). "Most recently, targeted RNA interference (RNAi) technology has been used to inhibit anthrax toxin intoxication through silencing ANTXR1 and/or ANTXR2 in mouse and human macrophages." (PMID 26805886, 2016). "Since PA is a ligand of ANTXRs, that finding not only supports our discovery that ANTXR2 and MT1-MMP interact, but suggests that this interaction might negatively regulate the process of anthrax intoxication." (PMID 22529944, 2012). "A few months later, after 2001 anthrax attack, tumor endothelial marker 8 (TEM8) was reported as an anthrax toxin receptor, hence being named anthrax toxin receptor 1 (ANTXR1), which was followed by the identification of CMG2 as the second anthrax toxin receptor (ANTXR2)." (PMID 26805886, 2016).
glioma (4 papers, 2019 to 2024). A benign or malignant brain and spinal cord tumor that arises from glial cells (astrocytes, oligodendrocytes, ependymal cells). "Cholesterol depletion induces ANTXR2-dependent activation of MMP-2 in glioma cells." (PMID 38023262, 2023).
ankylosing spondylitis (3 papers, 2014 to 2024). An autoimmune chronic inflammatory disorder characterized by inflammation in the vertebral joints of the spine and sacroiliac joints. "ANTXR2 mutations are connected to the development of Ankylosing Spondylitis (AS), a chronic inflammatory condition affecting the spine and sacroiliac joints." (PMID 38674361, 2024). "Previous studies have demonstrated associations of ANTXR2 gene polymorphisms with ankylosing spondylitis (AS)." (PMID 30255098, 2018). "ANTXR2 variants have been associated with ankylosing spondylitis (AS) in two previous genome-wide association studies (GWAS) (p∼9×10−8)." (PMID 25169729, 2014).
Hypertension (3 papers, 2020 to 2024). The presence of chronic increased pressure in the systemic arterial system. "We propose these SNPs as potential candidates for hypertension linked to the ANTXR2 gene, which is implicated in blood pressure regulation." (PMID 38674361, 2024). "We propose these SNPs as potential candidates for hypertension linked to the ANTXR2 gene, which is implicated in blood pressure regulation, possibly through angiogenesis or vascular contraction pathways." (PMID 38674361, 2024). "Recent genetic studies have implicated ANTXR2 gene coding for ANTR2 protein associated with hypertension as well as grip strength." (PMID 32762010, 2020).
Alzheimer disease (2 papers, 2023 to 2024). A progressive, neurodegenerative disease characterized by loss of function and death of nerve cells in several areas of the brain leading to loss of cognitive function such as memory and language. "Although most models showed no significant genes, the dominant PTV model showed significant case enrichment for ANTXR2 (OR = 174.57, p = 8.38 × 10–6), a gene associated with brain connectivity changes and Alzheimer’s disease." (PMID 38951798, 2024).
autoimmune disease (2 papers, 2016 to 2024). A disorder resulting from loss of function or tissue destruction of an organ or multiple organs, arising from humoral or cellular immune responses of the individual to their own tissue constituents. "Furthermore, three loci which previously have been implicated in JIA and several other autoimmune diseases – the PTPN22 locus on 1p13, the IL2RA locus on 10p15, and the ANTXR2 locus on 4q21.21 – were nominally associated with JIA." (PMID 27005825, 2016).
endometriosis (2 papers, 2020 to 2023). The growth of functional endometrial tissue in anatomic sites outside the uterine body. "The PCGEM1/miR-124-3p/ANTXR2 regulatory network is likely to be a novel therapeutic target in endometriosis." (PMID 36915057, 2023). "Taken together, these findings indicate that the lncRNA PCGEM1 and ANTXR2 are overexpressed in endometriosis." (PMID 36915057, 2023). "Furthermore, ANTXR2 has been reported to ameliorate endometriosis progression, and both the mRNA and protein levels showed a significant increase in endometriotic specimens." (PMID 36915057, 2023). "To interpret the biological functionality of the lncRNA PCGEM1 and anthrax toxin receptor 2 (ANTXR2) in endometriosis, we measured the PCGEM1 and ANTXR2 relative mRNA and protein expression levels in 10 paired ectopic (NE) and eutopic (Eu) endometrial tissues by qRT‒PCR and Western blot analysis." (PMID 36915057, 2023). "Furthermore, ANTXR2 inhibitor can prevent and reduce endometriotic lesion formation in the mouse model of endometriosis, revealing its therapeutic potential for endometriosis." (PMID 32389123, 2020).
Failure to thrive (2 papers, 2012 to 2020). Failure to thrive (FTT) refers to a child whose physical growth is substantially below the norm. "HFS resulting from ANTXR2 mutations is another multi-systemic disease that manifests with chronic diarrhea and failure to thrive in the severe forms." (PMID 33147779, 2020). "Patients with JHF and ISH, the human diseases caused by mutations in the ANTXR2 gene, develop symptoms after birth and clinical features of the diseases include skin fibromas, gingival hypertrophy, joint contractures, osteoporosis and in the case of ISH, a failure to thrive." (PMID 22529944, 2012).
ovarian carcinoma (2 papers, 2017 to 2020). A malignant neoplasm originating from the surface ovarian epithelium. "We designed gRNAs and ssODNs to delete a part of Antxr2, in the murine ovarian cancer cell line ID8." (PMID 33339985, 2020).
Cirrhosis (1 paper, 2023). A chronic disorder of the liver in which liver tissue becomes scarred and is partially replaced by regenerative nodules and fibrotic tissue resulting in loss of liver function. "Since the human liver NPCs scRNA seq data analysis showed that the proportion of ECs in the cirrhosis group changed the most and extracellular matrix-related pathways were enriched in endothelial cell differential genes, endothelial markers CD31 and ANTXR2 were first co-stained in the liver." (PMID 38322497, 2023). "Compared with the healthy group, the expression of ANTXR2 was downregulated in endothelial cells and upregulated in T cells in the cirrhosis group, but had no change in mononuclear phagocytes." (PMID 38322497, 2023).
fibrosis (1 paper, 2023). the formation of excess fibrous connective tissue in an organ or tissue in a reparative or reactive process. "When Antxr2 expression in liver ECs was decreased, liver repair may be inhibited, resulting in the aggravation of fibrosis, whereas increased Antxr2 expression in liver ECs after AAV treatment effectively improved liver fibrosis and restored normal liver function." (PMID 38322497, 2023). "Based on these findings, mice lacking endothelial Antxr2 showed more severe liver fibrosis after fibrosis modeling compared to controls." (PMID 38322497, 2023).
intestinal lymphangiectasia (1 paper, 2020). Dilatation of the intestinal lymphatic system usually caused by an obstruction in the intestinal wall. "Some HFS patients were reported to suffer from intestinal lymphangiectasia based on histological analysis, but it is unclear whether ANTXR2 deficiency leads to a primary defect of the epithelium as well." (PMID 33147779, 2020).
Liver fibrosis (1 paper, 2023). "Finally, endothelial-specific overexpression of Antxr2 alleviated the development of liver fibrosis following adeno-associated virus treatment." (PMID 38322497, 2023). "In this study, the mechanisms of liver fibrosis were explored and we report that a novel function of ANTXR2 in the liver and a potential therapeutic target for liver fibrosis." (PMID 38322497, 2023). "Collectively, these results suggested that endothelial ANTXR2 plays a protective role in liver fibrosis." (PMID 38322497, 2023). "After endothelial-specific Antxr2 knockout mice were subjected to the CCl4 model, the degree of liver fibrosis in the knockout group was significantly more severe than that in the control group." (PMID 38322497, 2023). "Taken together, these data suggested that ANTXR2 is the key factor regulating the activity of MMP2 in ECs, and that endothelial ANTXR2 plays a protective function in liver fibrosis." (PMID 38322497, 2023). "Because ANTXR2 promoted the activation of MMP2 to degrade the ECM, whether ANTXR2 overexpression might alleviate liver fibrosis was investigated." (PMID 38322497, 2023). "In summary, these data suggested that ANTXR2 functions as a switch in liver fibrosis." (PMID 38322497, 2023). "ANTXR2 expression in the liver endothelium of wild-type (WT) mice significantly decreased after a 4-time sequential injection of carbon tetrachloride (CCl4) to induce liver fibrosis." (PMID 38322497, 2023). "Liver fibrosis increased in endothelium-specific Antxr2 knockout mice after fibrosis modeling." (PMID 38322497, 2023). "Therefore, we focused on the effect of endothelial ANTXR2 expression on liver fibrosis." (PMID 38322497, 2023). "Therefore, we speculated that ANTXR2 also plays an important role in the liver fibrosis process." (PMID 38322497, 2023). "Liver fibrosis also results in excessive deposition of ECM; therefore, whether liver endothelial ANTXR2 plays an important role in the progression of liver fibrosis was investigated." (PMID 38322497, 2023). "We hypothesized that ANTXR2 serves as a bridge connecting ECs and the ECM, thereby influencing the occurrence and progression of liver fibrosis." (PMID 38322497, 2023).
vascular malformation (1 paper, 2025). A non-neoplastic disorder that is the result of defects of vascular morphogenesis. "Pathogenic variants of ANTXR2 have never been reported in association with congenital vascular malformations." (PMID 40259928, 2025).
tumor (18 papers, 2009 to 2025). "Both Tumor endothelial marker-8 (TEM8 or ANTRX1) and capillary morphogenesis gene-2 (CMG2 or ANTXR2) play a role in tumor angiogenesis, making them potential targets for cancer therapy." (PMID 39998073, 2025). "ANTXR2, also known as capillary morphogenesis gene 2 (CMG2), is involved in tumor angiogenesis, and activating ANTXR2 could promote the proliferation and vitality of ESCs." (PMID 39135784, 2024).
infection (5 papers, 2014 to 2023). The state of being infected such as from the introduction of a foreign agent such as serum, vaccine, antigenic substance or organism. "Deletion of CMG2/ANTXR2 in myeloid cells led to host resistance to infection with an uncapsulated strain in mice." (PMID 24763227, 2014).
bacterial infection (1 paper, 2019). "Th1 cell differentiation and activation are considered to be, at least partially, mediated by the anthrax toxin receptor 2, ANTXR2, which is selectively targeted by miR-124, and overexpression of ANTXR2 induces autophagy during bacterial infection in patients with AS." (PMID 31360722, 2019).
infectious disease (1 paper, 2007). A disorder directly resulting from the presence and activity of a microbial, viral, or parasitic agent in humans. "It is interesting that two anthrax toxin receptors, ANTXR1 (CEU vs. YRI) and ANTXR2 (EAS vs. YRI), show signatures of selective sweeps, which may indicate cases in human history of fights against specific infectious diseases." (PMID 17356696, 2007).
ANTXR2 also shares sentences with these, for which no sentence is quoted: cancer (12 papers); breast carcinoma (7); gastric cancer (6); prostate carcinoma (6); soft tissue sarcoma (4); GAPO syndrome (2); genetic diseases (2); infantile systemic hyalinosis (2); prostate tumor (2); Protein-losing enteropathy (2); alopecia (1); breast tumor (1); cardiovascular disease (1); colitis (1); connective tissue disorder (1); fibrosarcoma (1); glioblastoma (1); hyperopia (1); Intellectual disability (1); leiomyosarcoma (1); leukaemia (1); Lewis lung carcinoma (1); liposarcoma (1); lung carcinoma (1); lymph node metastasis (1); muscular dystrophy (1); myotonic dystrophy type 1 (1); optic atrophy (1); osteoporosis (1); pancreatic cancers (1).
A further 6 diseases each share a sentence with ANTXR2 in 1 paper.